TLR3 (toll like receptor 3)
Diseases named in the same sentence as TLR3 in open-access papers (continued):
Sharing a sentence is not in itself a finding about the gene and the disease.
viral infection (continued). "In the absence of a functional TLR3 pathway, infected mice exhibit increased vulnerability to viral infection, elevated viral loads both systemically and in infected tissue, and exacerbated pathologic symptoms and mortality rates." (PMID 39988665, 2025). "Through a combination of RT-qPCR and luciferase reporter assays, we demonstrate that E1 suppresses the production of interferons and interferon-stimulated genes triggered by viral infections and the activation of RIG-I/MDA5-MAVS, TLR3-TRIF, cGAS-STING, and JAK-STAT pathways." (PMID 40330484, 2025). "Although both RIGI and TLR3 pathways are known to be important for IFN induction by IAV, our experiments showed elevated signaling through the endosomal TLR3 pathway, providing evidence that the WD domain is protective against viral infection." (PMID 40143422, 2025). "Furthermore, poly (I:C) administration activates the TLR3/TBK1/IFN-β signaling cascade and induces proinflammatory responses in RAW264.7 macrophages, thereby mimicking a viral infection." (PMID 40909801, 2025). "Mammalian TLR3 can be activated by viral dsRNA or poly(I:C) analogs, which bind to each other to activate the adaptor protein TRIF and subsequently promote the production of interferon through signal transduction, promoting viral infection and replication." (PMID 39597653, 2024). "One possible explanation for this finding is that decreased CTSH gene expression may reduce the N-terminal cleavage of Toll-like receptor 3 (TLR3), impairing TLR3 functionality and dropping TI-IFN expression in response to viral infections in early childhood." (PMID 38398001, 2024). "For instance, TLR4 can remember LPS from Gram-negative bacteria, but TLR3 is known to recognize dsRNA that is generally generated during viral infections." (PMID 39483482, 2024). "Post-TLR3 silencing, a decrease in NF-κB mRNA expression was observed across all examined time points following H9N2 AIV infection (p < 0.005), underscoring its pivotal role in regulating NF-κB transcription in response to viral infection." (PMID 38731436, 2024). "Predominantly, TLR7, TLR3, and TLR4 are involved in sensing viral infections." (PMID 37515084, 2023). "SLR10 administration did not change RIG-I and TLR3 mRNA induction by virus infection in the lungs of CS mice (CS SLR10 PR8 vs. CS PR8)." (PMID 37475869, 2023). "When HCV dsRNA activates TLR3, IFN-β is produced, which can prevent replication of viral infection." (PMID 38173795, 2023). "Like in mammalian, several PRRs exist in chickens, such as TLR3, TLR7, and MDA5, which could also be activated by viral RNA to generate the antiviral immune responses during virus infection." (PMID 36960283, 2023). "Even though DDX50 was required for optimal signal transduction in response to agonists for RIG-I, MDA5, and TLR3, its absence did not abolish signalling in response to viral infection or stimulation." (PMID 35215908, 2022). "TLR3 is highly conserved across species and exerts non-redundant functions in the context of several viral infections across mice and humans." (PMID 35464475, 2022). "When nontreated ID8 and MCA205 cells were compared, higher basal levels of antiviral response genes (e.g., Cxcl10, Ifnb, Il1b) and lower basal levels of dsRNA sensor genes (e.g., Ddx58, Tlr3) were observed in MCA205 cells, which would limit viral infection/replication and detection, respectively." (PMID 34922008, 2022). "Since type I IFN signaling is critical for protection against several viral infections, rASP-1 stands to be a new addition to other known type I IFN stimulating adjuvants such as Poly I:C (TLR3 agonist), R848 (TLR7/8 agonist), CpG (TLR9 agonist) and STING agonists." (PMID 36119026, 2022). "Similarly, TRIF has been identified as an important adaptor of TLR3, TLR19, and TLR22 mediated signaling pathways and plays important roles in immune responses against bacterial and viral infections in teleosts." (PMID 35898509, 2022).
viral infection (continued). "In conclusion, it would seem as if APOLs were evolutionary generated as instruments to limit viral infection through their involvement in PI4KB‐dependent autophagy and autophagy‐related apoptosis, following their strong induction by the virus‐activated TLR3/TRIF pathway." (PMID 32530132, 2021). "Moreover, virus infection-induced TNFAIP3 can block the phosphorylation and dimerization of IRF3 and inhibit the TLR3-induced activation of NF-κB and IFN-β." (PMID 34781747, 2021). "Although the role of viral infections in CRSwNP development is not clear, herein we showed that the TLR3 agonist and viral analogue poly(I:C) promoted a Th2-skewed environment in neutrophilic nasal polyp development." (PMID 33441902, 2021). "RNA sensor TLR3 is identified by detecting extracellular viral nucleic acids during viral infection, while RNA sensor PKR does not signal directly to type I IFN production." (PMID 33976210, 2021). "In fact, we found that OECs treated with poly(I:C), a TLR3 agonist simulating a viral infection, did not completely prevent T cell activation." (PMID 35126344, 2021). "The Toll-like-Receptor 3 (TLR3) is critical in the recognition of viral nucleic acids to initiate innate antiviral immune responses, including the generation of type I, type II, and type III interferons (IFNs), to provide protection against viral infection." (PMID 33657175, 2021). "TLR3 recognizes dead virus-infected cells and generates IFN-1 as well as the proinflammatory cytokines TNF, IL1, and IL6, allowing the host to develop a defense against viral infections." (PMID 34659656, 2021). "TLR-3 mediates viral double-strand RNA recognition, and IRF-3 is essentially involved in regulating TLR-3-induced interferon-β gene transcription in response to viral infections." (PMID 32734144, 2020). "TLR3 has been found to be up-regulated in IBDV-infected chickens, and the function of this TLR has been considered vital to innate responses to viral infection." (PMID 33193617, 2020). "We tested the ability of HLCs to respond to ligands for PRRs (RIG-I/MDA5; TLR3, 7, 9); type I IFN, the principle activator of innate anti-viral genes; type III IFN, the main IFN expressed in hepatocytes upon viral infection; and TNF-α, an inflammatory cytokine produced early in viral infection." (PMID 32481600, 2020). "Viral recognition receptors, such as toll-like receptor 3 (TLR3) expressed by epithelial cells, are activated to produce inflammatory cytokines and chemokines, including thymic stromal lymphopoietin (TSLP), CCL26, and CXCL8 when viral infection occurs." (PMID 32120846, 2020). "In the infected cells, TLR3 can recognize dsRNA and activate TBK1 by acting on the TRIF-dependent pathway; then, phosphorylated IRF3 is induced to translocate into nuclei; finally, it can induce the secretion of cytokines IFN-β against viral infection." (PMID 31975996, 2019). "The prolonged inflammatory response induced by TLR3 activation in microglia and astrocytes biologically serves to control or to enhance insidious viral infections such as Chikungunya and HIV-1 and non-viral infections such as Borrelia burgdorferi." (PMID 30971945, 2019). "For PEF, interactions between viral infection and RIG-I and TLR3 mRNA were also seen." (PMID 30463560, 2018). "In addition, the investigation also showed that the effective expression of the host TLR3 was established by establishing a robust innate immune response with the KRAS‐mutant HCT116 cell line 79, which inhibited the potential of the virus infection." (PMID 29658188, 2018). "Although plasmacytoid DCs are important cells in the response to viral infection, they do not express TLR3." (PMID 28973047, 2017). "Therefore, we believe the contribution of ERK1/2 activation to the viral infection-induced GC action occurs upstream of TGF-β expression, in signaling emerging from activation of TLR3." (PMID 28046097, 2017).
viral infection (continued). "Where several studies describe the role of TLR4 during viral infection, as TLR4 is upregulated in response to CVB3 inoculation on the plasma membrane and contributes to its pathogenesis, the contribution of especially TLR3 and TLR5 is less founded." (PMID 27878326, 2017). "Our findings reveal that SAMHD1 could be activated by the same signals that trigger type I IFN production, via TLR3 and RIG-I/MDA5 signaling pathways, soon after viral infection." (PMID 27411355, 2016). "We show that the TLR3 and RIG-I/MDA5 pathways participate in the regulation of SAMHD1 expression and find that IRF3 phosphorylation and nuclear translocation are critical aspects of SAMHD1 upregulation after IFN-α treatment and virus infection." (PMID 27411355, 2016). "IRF2 binds to TLR3 and other IFN-inducible gene promoters and maintains an active chromatin structure in the unstimulated state, which is required for their induction, while IRF1 binding to these promoters activates their transcription upon viral infection." (PMID 25960866, 2015). "Overall, our RNA-seq data provide novel insights into the transcriptional landscape TLR3 and TLR4 ligands mimic certain aspects of viral infection by triggering key molecular events such as a rapid innate immune response during the early course of the inflammatory response." (PMID 26159724, 2015). "One of the key genes that plays a role in response to viral infections is the toll-like receptor 3 (TLR3), after viral infection TLR3 recognizes double strand RNA (dsRNA) that leads to downstream activation of type I interferons and NF-κB, a proinflammatory and prosurvival pathway." (PMID 24435511, 2014). "However in PAMs, TLR3, TLR7, and TLR8 mRNA expressions were significantly up-regulated by the viral infection." (PMID 24712747, 2014). "Both RIG-1 and TLR3 have been recognized as important PRRs in viral infection, but their roles in JEV-infected microglia are not fully understood." (PMID 25101306, 2014). "This is interesting since TLR3 is involved in inflammatory responses upon viral infections and could explain AOSD flares upon viral infections." (PMID 23424598, 2013). "Agonists of TLR3 and TLR7-9 yielded very promising results for treating viral infections." (PMID 24302927, 2013). "The role of Tlr3 during viral infection is not uniform and both beneficial as well as detrimental effects of Tlr3-mediated immune activation have been noted." (PMID 22570612, 2012). "TLR-3 in the liver may mediate innate activity and inflammation and induces type I IFN production during viral infections." (PMID 22114589, 2011). "Interestingly, studies have also demonstrated that expression of TLR3 and RIG-I are also reduced in HCV patients, therefore we decided to examine if there is a correlation between the expression of these receptors and virus infection." (PMID 21695051, 2011). "Therefore, TLR3-mediated signaling during chronic viral infection, particularly infections leading to immune-mediated diseases, appears to be protective, whereas premature activation of the signals prior to and/or at the time of viral infection may exacerbate the pathogenesis." (PMID 22189096, 2011). "Moreover, understanding how TLR3 is activated and regulated in immune cells and IEC can help to choose effective therapies for the prevention or treatment of viral diseases in humans and pigs." (PMID 22046952, 2011). "It is possible that the resident cells such as keratinocytes, macrophages, and dendritic cells could be responding to virus infection by up-regulating the antiviral IFN-γ and TLR-3 transcription." (PMID 20711354, 2010). "In our patients, SAMHD1 was not expressed when mimicking viral infection in vitro using the Toll-like receptor-3 (TLR3)-agonist Poly(I:C)." (PMID 20842748, 2010).
viral infection (continued). "At 48 hours post-infection, we observed that both NK and NKT cells from TLR3KO mice upregulated CD69 to levels comparable with WT NOD mice suggesting that these cells can respond normally to viral infection despite the absence of TLR3 signaling." (PMID 19122812, 2009). "Mice lacking TLR3 succumb rapidly to viral infection due to uncontrolled viral replication leading to a rapid increase in cardiac damage." (PMID 19122812, 2009). "However, starting at 18 hours pi, titers from MDA5−/− BMDCs began to increase over WT and TLR3−/− BMDCs, and leveled out to a significant difference at 24 and 48 hours, indicating that MDA5 recognition occurs late in viral infection." (PMID 18636103, 2008). "No external signals, such as viral infection or injury, are required to induce TLR3 activation." (PMID 40647457, 2025). "Exogenous NO decreased the interferon response pathway (IFR) in a dose-dependent manner for both HSV-1 and poli (I:C), a TLR3-dependent inducer of IFR pathway, which may indicate the existence of a back-loop mechanism, serving as stop signal upon viral infection." (PMID 41156686, 2025). "To mimic bacterial and viral infections we used a panel of three stimuli (lipopolysaccharide (LPS), resiquimod (R848), and polyinosinic:polycytidylic acid (Poly I:C)) to stimulate the extracellular Toll-like receptor (TLR) 4 and the intracellular TLR7/8 and TLR3, respectively." (PMID 36059528, 2022). "However, differential roles for the RNA-sensing PRRs during viral infections of the CNS have been identified, most notably for West Nile Virus (WNV), where TLR3, TLR7, and RLR receptors RIG-I and MDA-5 have been shown to coordinate and propagate a protective response." (PMID 35584192, 2022). "Poly(I:C) is a dsRNA analogue and TLR3 agonist that mimics several biological effects of viral infection without being subject to the variation in intensity that may apply to actual infections." (PMID 34950134, 2021). "Our observation that CLEC18A acts as a TLR3 co-receptor is the first step to explore its potential role in innate immunity against viral infection, and more studies are necessary to understand how CLEC18A contributes to host innate immunity against viral infections in the future." (PMID 33603190, 2021). "Notably, the effect of famotidine treatment was on TLR3 mRNA and protein expression is independent of viral infection and can be seen at a similar extent in uninfected cells." (PMID 34214498, 2021). "It was shown that HSV-1 could induce TLR7 expression at later phase after virus infection, and the induced TLR7 expression was coincident with the declined expression of TLR3, implicating that TLR3 and TLR7 might act sequentially to response to viral infection and replication in HCECs." (PMID 31889912, 2019). "Therefore, to mechanistically delineate the contribution of macrophages to CCL2 production during viral infection, monocyte-derived macrophages were stimulated with purified viral PAMPS, poly I:C, a TLR3 agonist, and ssRNA40, which is derived from the HIV-1 long terminal repeat and activates TLR7/8." (PMID 29466439, 2018). "We and others have demonstrated that epithelial cells from different organs and regions possess functional TLR3/RIG-I signaling systems, which could be immunologically activated by Poly I:C to trigger the immune responses against viral infections, including HSV-2." (PMID 30322047, 2018). "Moreover, it is known that TLR3 signalling is not required for the initial cell-autonomous recognition of viral infection or the induction of IFNα, which is induced via viral recognition by RIG-I." (PMID 27825367, 2016). "The TLR3 induced expression of TSLP introduces a mechanism by which the Th2-skewed tissue environment might arise in nasal polyps and invites a further evaluation of the potential contribution of current or past viral infections to polyposis pathogenesis." (PMID 27050744, 2016).
viral infection (continued). "In our previous study, we confirmed that TLR3 was expressed in NCI-H292 cells, a human pulmonary mucoepidermoid carcinoma cell line, and a synthetic dsRNA analogue, poly(I:C), used as a TLR3 ligand to mimic viral infection, induced the expression and release of MUC5AC from the cells." (PMID 27677339, 2016). "The increased expression of dsRNA receptor TLR3 and IFN induced genes ISG56, ISG43, Mx1 and IFIT3 after stimulation with poly I:C mimicking a viral infection indicates that these cell lines can be used as effective in vitro models to study the bat's innate immune responses to virus infection." (PMID 25295526, 2014). "Moreover, our review of medical records revealed that 9 of the 11 patients with both HLA-A*0206 and TLR3 SNP rs3775296T/T (and rs.5743312T/T) developed SJS after receiving cold medicine, leading us to suspect that they already had a viral infection before taking the cold medicine." (PMID 22912896, 2012). "In the context of a viral infection, however, we note it is likely that fully assembled virions may not result in activation of TLR3 signaling if the dsRNAs are not exposed." (PMID 22016778, 2011). "Finally, rhinovirus infection activates TLR3 in BEAS2B cells in the absence of exogenous dsRNA ligands, suggesting that TLR3 recognizes intracellular viral or cellular RNAs, as would be the case during viral infection." (PMID 22039520, 2011). "While the early adaptive immune response to viral infections was not altered in the absence of TLR3-mediated signals, consistent with a previous report, cellular infiltration into the CNS was markedly elevated, resulting in exacerbation of TMEV-induced immune-mediated demyelinating disease." (PMID 22189096, 2011). "Recently evidence for this hypothesis has been found in mice, where necrotic cell death stimulated TLR3 activation and subsequent inflammation, independent of viral infection." (PMID 20360967, 2010). "Although this functional alteration may impact the activation of TLR3-mediated immune responses, influencing the intensity of the inflammatory response during viral infections, it did not demonstrate a direct relationship with the manifestation of various symptoms of diseases associated with HTLV-1." (PMID 40831704, 2025). "Unlike TLR3–IFN deficiency, which has also been reported in patients with severe viral diseases of tissues other than the brain, such as severe influenza and COVID-19 pneumonia, deficiencies of snoRNA31, RIPK3 and DBR1 have not yet been detected in patients with viral infections of other organs." (PMID 39048830, 2024). "Furthermore, IFN-β expression in response to viral infection is known to be absent in Huh-7 cells due to defects in the TLR3 and RIG-I pathways, and this likely accounts for the greater number of genes associated with the RIG-I pathway induced in HepG2 cells in our experiments." (PMID 32251473, 2020). "However, no report has elucidated the relationships between TLR3 signaling and ciliary activity during viral infection, which is critical given that ciliary activity is a major determinant of the ability of mucociliary clearance to eliminate noxious viruses from the respiratory tract." (PMID 33109186, 2020). "When we treated cells with EGCG before HCV dsRNAs stimulation, the HCV dsRNAs-induced IFN-λ1, RIG-I, TLR3 and several antiviral ISGs (ISG15, MxA) expressions were significantly enhanced, indicating that EGCG might be used as an agent to enhance the innate immune responses during viral infections." (PMID 26879672, 2016).